CD4 (CD4 molecule)
Diseases named in the same sentence as CD4 in open-access papers (continued):
Sharing a sentence is not in itself a finding about the gene and the disease.
tumor (continued). "A recent study showed that PD-1 expression on CD4+ cells associates with the tumor size and that neutrophils are the most abundant immune cell type in NSCLC7." (PMID 31316109, 2019). "CD8+ T cells and type-1 helper CD4+ T cells (Th1) are thought to play a major role in effective anti-tumor responses, and thus associate to good prognosis in most human cancers." (PMID 30984190, 2019). "Increased NF-κB signaling in CD4+ T cells has been linked with increased anti-tumor response by increased secretion of granzyme B, TNF-α (tumor necrosis factor alpha), and interferon-γ." (PMID 31394796, 2019). "While anaphylatoxins can lead to engagement of immune-evading mechanisms, localized activation of intracellular complement in T cells can lead to production of CD4+ subpopulations which are associated with inhibition of tumor progression." (PMID 31134065, 2019). "The density of mature DCs (DC-LAMP+) is highly correlated with the density of infiltrating CD4+ and T-bet+ T-cell into tumor, which also is associated with a favorable long-time survival of patients." (PMID 31281318, 2019). "During the in vitro culture, the expression of PD-1 decreased sharply at the early stage either on CD8+ or on CD4+ T cells because loss of the tumor microenvironment, then the expression PD-1 increased sharply because of stimulation by anti-CD3 antibody." (PMID 31827396, 2019). "Our results show that this improved response of immunologically cold 9464D-GD2 to RT and combined IT-IC, anti-CTLA-4, CpG, and anti-CD40 is associated with increased CD4+ T cell infiltration and decreased presence of Tregs within the tumor microenvironment." (PMID 31810498, 2019). "The patient with refractory tumor after treatment received a second adoptive T cell transfer which contained more than 95% ERBB2IP mutation specific CD4+ T cells." (PMID 30473928, 2018). "In particular, TAMs, dendritic cells, tumor-associated mast cells, myeloid-derived suppressor cells, natural killer (NK) cells, invariant natural killer cells, and CD4+ and CD8+ T cells have been shown to play a role in TC." (PMID 29953504, 2018). "In CD4+ T cells, for instance, inhibitory genes were upregulated by tumor-derived exosomes, which led into a loss of CD69 on their surface and a functional decline of these cells." (PMID 29515996, 2018). "On the other hand, lymphocytes are thought to have an anti-tumor effect, since it is now known for a long time that tumor infiltration of CD4+ and CD8+ cells is associated with improved survival in RC patients." (PMID 29854285, 2018). "Others have shown that tumor vessel “normalization” is associated with CD4+ T cell infiltration (reflecting vascular and immune reprogramming), and results in fewer metastases and a better survival." (PMID 30248111, 2018). "A DNA vaccine encoding a tumour specific CD8 epitope fused to a universal CD4 epitope showed enhanced immune responses." (PMID 29570634, 2018). "This was associated to lower levels of tumor-associated CD4(+)Tregs in MIF (-/-) than MIF(+/+) mice." (PMID 29707160, 2018). "Mechanistically, maximal anti-tumor activity of cytokine mRNAs was associated with multiple immune populations including CD4+ and CD8+ T cells as well as NK cells." (PMID 30400822, 2018). "Immune suppressive cell types that have been shown to influence ICI efficacy in pre-clinical models include Tregs, MDSCs, Th2 CD4+ T cells, and M2-polarised tumour-associated macrophages." (PMID 29319049, 2018). "A very recent characterization of tumor-associated T cells via a customized time-of-flight mass cytometry (CyTOF) revealed the presence of PD-1+ CD4+ effector and PD-1− CD4+ regulatory T cells as potential complementary mechanisms of local immunosuppression." (PMID 30473768, 2018). "Once the tumor is established, tumor cells secrete cytokines IL-4, IL-10, IL-13 and lactic acid, and along with the presence of CD4+ Th2 cells, cause the polarization of TAMs toward an M2-like phenotype." (PMID 30356656, 2018).
tumor (continued). "In humans, adoptive transfer of tumor-specific CD4+ T cells caused a complete tumor eradication in a patient bearing cholangiocarcinoma, another primary liver cancer." (PMID 29795111, 2018). "In our study, the frequencies of specific tumor-associated CD4+ T cell subsets, which can be distinguished by markers such as Th2, Th1 or Th17 cytokines, were not determined." (PMID 30112116, 2018). "Our recent study found that intrahepatic CD4+ T cells are an indispensable component of anti-tumor surveillance in NAFLD, and linoleic acid (C18:2) causes CD4+ T cell apoptosis by impairing electron transport chain (ETC) function and generating ROS8." (PMID 29795111, 2018). "High levels of infiltration (> 60% of metastatic tumour cell nests containing lymphocytes) by CD4+ and CD8+ T cells was significantly associated with a pCR (p = 0.004 and p = 0.001, respectively) following NAC." (PMID 29390966, 2018). "This has important implications for associated mechanisms of tumor-directed CD4 T cell responses that will be discussed in the next section." (PMID 29032503, 2018). "Gal-1 deficiency in CD4+ T cells was shown to impair T cell migration to the tumor site, whereas tumor-derived Gal-1 was shown to promote metastases accompanied by reduced tumor infiltration by immune cells." (PMID 29682521, 2018). "Consistent with this, we observed that higher numbers of all CD8+ T-cells and of venus+ CD8+ T-cells in the tumor were well-associated with the suppression of tumor growth resulting from anti-PD-1/4-1BB or anti-CD4 mAb therapy." (PMID 29348598, 2018). "We aimed to identify immunogenic peptides derived from tumor mutated proteins that stimulated CD4+ T cells responses thus favoring the exceptional recovery process of this patient." (PMID 30459932, 2018). "High levels of tumor-associated macrophages (TAMs), CD4+ (helper) T cells, and T regulatory cells (Tregs) have all been implicated in favoring tumor progression." (PMID 30613350, 2018). "While accumulation of CD4+ Treg within tumors is associated with worse prognoses in many cancers, CD4+ T helper cells are required to optimize cytotoxic CD8+ T cell responses against tumor cells." (PMID 30505306, 2018). "The vaccinated group also showed a marked increase in infiltration of antitumor cells (natural killer, CD8+ T and CD4+ Th1 cells), as well as a decrease of myeloid-derived suppressor cells (MDSCs) and tumor-associated macrophages (TAMs)." (PMID 29755647, 2018). "More importantly, reduction in tumor progression in Dox-treated animals was strongly associated with reduced CD4+Foxp3+ Treg cell infiltration within tumor tissue as well as in tumor-draining lymph nodes (dLN)." (PMID 30413714, 2018). "Further improvement was associated with an increase in tumor infiltrating and activated CD4+ and CD8+ T-cells populations, and generation of memory T-cells." (PMID 30176921, 2018). "High C5a producing tumors showed a significant increased tumor progression associated with an overall decrease CD4+ and CD8+ T cells in the tumor." (PMID 30208949, 2018). "Given the large proportion of Tregs within the CD4+ population in tumor lesions, it is tempting to associate the presence of CCR4+ effector cells to Tregs." (PMID 30420855, 2018). "Similar results have been reported with regard to invariant natural killer T cells (iNKTs), myeloid-derived suppressor cells (MDSCs), and tumor-associated macrophages (TAMs), along with diminished CD4+ T helper cells." (PMID 30104473, 2018). "Reduced levels of GP38 correlated with a high proportion of overall and CD4+ TILs, which contribute to tumor suppression, thus supporting an association between tumor immune status and overall survival in patients with BC." (PMID 29698574, 2018). "Accumulation of Tregs at the tumor site is associated with reduced survival of ovarian cancer patients, as are high CD4/CD8 ratios." (PMID 29342108, 2018).
tumor (continued). "Clinical trials using long peptides or mRNA to deliver CD4 T cell epitopes to dendritic cells have shown success in inducing mutant peptide-specific CD4 T cells and their association with anti-tumor efficacy." (PMID 30075702, 2018). "Immunohistochemistry on pancreatic cancer samples showed a higher cellular infiltration compared to normal pancreas and survival studies have shown that higher levels of tumor infiltrating CD4+ and CD8+ T cells are associated with longer survival." (PMID 29868007, 2018). "In order to clarify the immunological mechanisms underlying the pattern of tumor growth and survival in the animals re-challenged with the tumor, CD4+ and CD8+ T cells as well as Tregs were evaluated in blood." (PMID 29423067, 2018). "The associations between CD4+/PD-1+ or CD4+/PD-1− tumor-infiltrating lymphocytes and pathological characteristics were evaluated." (PMID 30069490, 2018). "In conclusion, we demonstrated that the excessive expression of FOXP3 in tumor-infiltrating CD4+ T cells of CRC patients is caused, at least in part, by the upregulation of STAT5 and TET2." (PMID 30013992, 2018). "Three out of 20 neopeptides were recognized by patient’s PBMC suggesting the presence of tumor-specific CD4+ T cell memory responses, potentially implicated in HCC elimination." (PMID 30459932, 2018). "IL-17E was expressed by tumor infiltrating CD4+ T cells and macrophages, and inhibition of IL-17E caused reduced tumor infiltration by both types of leucocytes, which was associated with a significantly disabled lung metastasis formation." (PMID 30518157, 2018). "Concordant with observations in peripheral T cells, tumor associated CD4+ T cells retain higher levels of CD28 expression than CD8+ T cells." (PMID 30400835, 2018). "IL-2/CD40 reduced CD25 and IFN-γ in tumor-associated CD4+ T cells in both age groups alongside reductions in the regulatory markers CD73 and CTLA-4." (PMID 30560130, 2018). "Secondly, recolonization of Akkermansia muciniphila and Enterococcus hirae associates with appearance of CD4+ central memory T cell (TCM) in tumor bed." (PMID 30139382, 2018). "It has been reported that chimeric Ii can be used as a vector for the efficient delivery of tumor-associated antigens to class II for subsequent presentation to CD4+ T cells." (PMID 29555965, 2018). "Consistent with other studies 27, 28, 40, combined depletion of CD8 and CD4 subsets completely abrogated any tumor regression or survival benefit associated with Treg depletion." (PMID 28250921, 2017). "CD4+ T cells with NKG2D positive expression were reported in patients bearing tumour or inflammation‐associated diseases." (PMID 28224733, 2017). "The association between tumor-infiltrating CD4+ T cells and tumor angiogenesis led us to further test the association between angiogenesis and a subset of immune inhibitory CD4+ T cells or regulatory T cells (Tregs)." (PMID 29163521, 2017). "These deficiencies can be overcome by transducing primary CD4+ T cells with tumour‐specific HLA class I‐restricted TCRs prior to adoptive transfer." (PMID 27324616, 2017). "Analysis of CD45+, CD3+ and CD4+ subset composition revealed that subgroups of immune cells associated with tumour or normal lung." (PMID 28146145, 2017). "Tumor-associated macrophages (TAMs) are alternatively activated cells that are induced by interleukin-4 (IL-4)-releasing CD4+ T cells." (PMID 29197379, 2017). "We examined HLA-A/-B/-C, B2M, and PD-L1 expression on thirty-six NF1-associated tumor samples by immunohistochemistry, and correlated these with tumoral CD4+, CD8+, FOXP3+, CD56+, and CD45RO+ lymphocytic infiltrates." (PMID 29137242, 2017). "These responses were associated with generation of T cells specific to the tumor and induction of specific anti-tumor immunity, which required both CD4+ TH cells and CD8+ CTLs." (PMID 28116088, 2017).
tumor (continued). "Ma found NAFLD causes selective CD4+T lymphocyte loss due to its high level of mitochondrially derived reactive oxygen species in fatty acid metabolism, and the impaired anti-tumor surveillance promotes hepatocarcinogenesis." (PMID 29221151, 2017). "Radiofrequency ablation alone has also been shown to cause a persistent increase in tumor specific antibodies, CD4+ T cells, CD8+ T Cells and to decrease levels of CD25+ FoxP3+ regulatory T cells." (PMID 29037259, 2017). "In a recent phase I/II clinical study a combination of LAG-3 Ig and peptides from five tumor-associated antigens was able to induce antigen-specific CD4 and CD8+ T cell responses in metastatic melanoma patients." (PMID 29033936, 2017). "For instance, castration was shown to cause induction of strong anti-tumor CD8+ T cell responses but these changes were accompanied by a concomitant increase in CD4+CD25+FoxP3+ T regs." (PMID 28134800, 2017). "Consistent with the immunofluorescence results, IL-25 expression in tumor-associated CD4+ cells and macrophages was >50 folds higher than in CD45- cells." (PMID 27909985, 2017). "We found that mice with selective Atg5 deficiency in CD4 T cells featured reduced tumour growth over controls." (PMID 28916785, 2017). "This resulted in a significant decrease in tumor growth and increased survival, associated with increased T cell tumor infiltration and a reduction in CD4+ Foxp3+ T cells in the tumor microenvironment." (PMID 29371976, 2017). "In particular, PD1 expressing CD4+ T cells were the only subset to associate with both tumour size and clinical stage in our cohort, which points to a potentially important role for this poorly understood cellular subtype." (PMID 28146145, 2017). "The association of tumor-infiltrating Tim-3+ PD-1+ CD4+/CD8+ T-cells with clinicopathological parameters was further analyzed in cancer patients." (PMID 29213216, 2017). "In tumours, >40% of CD4 cells in TLR-deficient mice displayed an activated phenotype, defined as CD62L−/CD154+." (PMID 28300057, 2017). "We investigated four markers of TILs and found that high levels of CD4+ lymphocytes in tumor-associated stroma to be significantly associated with survival." (PMID 26871598, 2016). "That initial assessment of peripheral blood mononuclear cells (PBMC) showed a significant increase in shared tumor associated antigen specific CD4+ and CD8+ T cell activation." (PMID 27330811, 2016). "The expression profiles of the inducible T cell co-stimulatory (ICOS) molecule were of particular interest because this T cell activation marker is known to increase on CD4+ T cells within the tumor and periphery following anti-CTLA-4 treatment." (PMID 26961085, 2016). "High ph-STAT3 tumour cell expression was negatively associated with tumour necrosis (P=0.001) and cellular inflammatory infiltrate as measured using CD4+ helper T-lymphocytes (P=0.024)." (PMID 27769057, 2016). "The presence of MHC class II-restricted CD4+ T cells that are specific for tumor-associated antigens has been recognized as an important element for providing helper factors essential for eliciting and sustaining cytotoxic CD8+ responses against tumors." (PMID 27576783, 2016). "Our data showed a clear decrease in Nrp-1 obviously in IL10-deficient tumor-bearing mice, and the number of CD4+Foxp3+Nrp-1+ T cells obtained from the spleen was significantly decreased in IL10−/− B16/F10 mice based on flow cytometry analysis." (PMID 27075020, 2016). "This approach has translated clinically, as a patient with metastatic cholangiocarcinoma displayed tumor regression after adoptive transfer therapy of CD4+ TILs specific for a mutated epitope identified during tumor sequencing." (PMID 27004405, 2016). "IDO1-expression is associated with increased differentiation of naïve CD4 T cells into Tregs in humans, and with increased infiltration of Tregs in tumor." (PMID 27192116, 2016).
tumor (continued). "Our data suggest that IL-10 is closely linked to tumor-associated CD4+ populations expressing either IFN-γ or IL-17A, whereas the presence of TGF-β appears to be of secondary importance." (PMID 27075020, 2016). "The frequencies of tumor-infiltrating CD4+ T cells were previously associated with longer disease-free survival periods and better prognosis." (PMID 27136203, 2016). "Collectively, our data indicate that Nrp-1 deficiency in CD4+Foxp3+ regulatory T cells in combination with increased Th1 and Th17 cell immunity results in decreased tumor growth, although elevated expression of Tregs is detected in IL-10−/− B16/F10 mice." (PMID 27075020, 2016). "Surprisingly, abrogation of IL-10 led to the promotion of tumor-associated Nrp-1 expression on CD4+ T cells only after TGF-β Ab treatment." (PMID 27075020, 2016). "The main mechanisms for the tumor escape mediated by HLA-G were an expansion of blood myeloid-derived suppressor cells (MDSCs), loss of peripheral CD4+ and CD8+ T cells, and a cytokine profile in favor of Th2 versus Th1/Th17." (PMID 27999823, 2016). "Tumor infiltrating CD4+T cells isolated from the SIRT1-deficient groups had a higher IL-9+ ratio than the WT group." (PMID 27589682, 2016). "Our results show that Id-specific CD4+ T cells were able to reject MHC II deficient MOPC315 cells, conclusively demonstrating that CD4+ T cells can kill MHC IINEG tumor cells." (PMID 27626487, 2016). "Mostly, this unique set of mutations, the mutanome, was recognized by CD4+ T cells and a vaccination approach with antigens recognized by CD4+ T cells indeed resulted in strong anti-tumor activity." (PMID 27060000, 2016). "This is also underlined by our findings that CD4+ T cell numbers were increased in the tumor and TDLNs as well as the ability of both CD4+ and CD8+ T cells to produce IFN-γ." (PMID 26741508, 2016). "In conclusion the data show that RT+L19-IL2 causes anti-tumour immune effects also outside the radiation field, and that this effect is associated with an increase of CD4+ T cells." (PMID 27994647, 2016). "PD-1/CTLA-4 blockade markedly increases EBV-specific T cell responses, and is associated with enhanced tumor infiltration by CD4+ and CD8+ T cells." (PMID 27186886, 2016). "In contrast, high ph-STAT3 tumour cell expression was associated with down-regulation of the local inflammatory infiltrate as evidenced by decrease in the CD4+ T-lymphocytes." (PMID 27769057, 2016). "In fact loss of tumor specific T cells of CD4, CD8 and NK T cell subsets is a hallmark for progression from MGUS to MM." (PMID 26784207, 2016). "This protective effect was associated with significant reduction in tumor-infiltrating FoxP3+ and IL-10+ Treg cells, and a corresponding increase in tumor-infiltrating CD4+ and CD8+ T cells that secreted IFN-γ." (PMID 26941742, 2016). "In HCC patients, high levels of tumor-infiltrating CD4+ T lymphocytes are associated with a lower recurrence rate and better prognosis." (PMID 27833084, 2016). "A high level of Foxp3+CD4+ T cells infiltration in the tumor stroma was found to be independently associated with the better overall survival (Exp(B), 3.69; 95 % CI of Exp(B), 1.05–12.96; P = 0.041)." (PMID 26604855, 2015). "Here, we scrutinized the effect of pre-vaccination immune regulatory cells on the immunological and clinical outcome of an anti-tumor vaccination, demonstrating that particularly the frequency of IL-17-secreting CD4+ T cells is associated with these endpoints." (PMID 26176858, 2015). "Firstly, lipid accumulation by tumor-associated CD4+CD8α-, CD4-CD8α- and plasmacytoid DCs implied that these subsets were impaired, however further functional studies such as antigen uptake and presentation assays and migration assays are required." (PMID 25886502, 2015). "B cell malignancies are exceptional amongst cancers in that they are derived from antigen-presenting cells that express MHC class II and can potentially present tumor-associated antigens to CD4+ T cells." (PMID 25941795, 2015).